MMP9 (matrix metallopeptidase 9)
Diseases named in the same sentence as MMP9 in open-access papers (continued):
Sharing a sentence is not in itself a finding about the gene and the disease.
pancreatitis (15 papers, 2009 to 2024). Inflammation of the pancreas. "Further studies showed that neutrophil MMP-9 promotes neutrophil migration, pancreatic trypsinogen activation, and pancreatitis-associated lung injury in vivo." (PMID 32411205, 2020). "A murine model of acute coxsackievirus B4-induced pancreatitis have also shown increased levels of MMP-9." (PMID 35041718, 2022). "MMP-9 activity was also significantly increased in the pancreas in acute pancreatitis animal models, and the severity of pancreatitis was significantly attenuated by treatment with an MMP inhibitor and in MMP-9-deficient mice." (PMID 36289761, 2022). "In acute pancreatitis models, MMP-9 was significantly increased in the pancreas, and the severity of pancreatitis was significantly reduced by treatment with an MMP inhibitor and in MMP-9-deficient mice." (PMID 34830195, 2021). "Certain MMPs, particularly MMP-9, have been reported to be closely related to pancreatitis severity and distant organ damage in different experimental models of pancreatitis as well as patients with AP." (PMID 32411205, 2020). "Firstly, we found that pancreatic MMP-9 was significantly upregulated, and serum MMP-9 was also elevated in caerulein-induced pancreatitis." (PMID 32411205, 2020). "Pancreatic MMP-9 was markedly upregulated and serum MMP-9 was increased in caerulein-induced pancreatitis." (PMID 32411205, 2020). "In caerulein-induced pancreatitis, we measured pancreatic MMP-9 mRNA and protein levels by qPCR and western blotting and found that both mRNA and protein levels of MMP-9 were markedly upregulated in caerulein-induced pancreatitis." (PMID 32411205, 2020). "(B) qRT-PCR for Egfr, Egf, Tgfα, Mmp2 and Mmp9 expression in fibroblasts freshly sorted from control normal pancreata, iKras* pancreata 3 weeks post pancreatitis, iKras* and iKras*;CD11b-DTR pancreata 3 days post Kras* inactivation and DT treatment." (PMID 28980940, 2017). "(A) qRT-PCR for Egf, Tgfα, Hbegf, Areg, Ereg, Mmp1, Mmp2, Mmp9, Mmp12 and Mmp14 expression in littermate control, iKras* pancreata 3 weeks post pancreatitis, iKras* and iKras*;CD11b-DTR pancreata 3 days post Kras* inactivation and DT treatment." (PMID 28980940, 2017). "In a recent rodent study on experimental SAP MMP-9 was found to be substantially elevated in the kidney within 12 h of the induction of pancreatitis preceding a later rise in serum creatinine." (PMID 27561093, 2016). "In a recent rodent study on experimental SAP, MMP-9 was found to be markedly elevated in the kidney within 12 h from the induction of pancreatitis preceding a later rise in serum creatinine." (PMID 27561093, 2016). "Previous reports have demonstrated that MMP-9 was significantly increased in the pancreas in an acute pancreatitis model, and both the severity of pancreatitis and the infiltration of leukocytes into the pancreas were reduced considerably in treatment with an MMP inhibitor and MMP-9-deficient mice." (PMID 34830195, 2021). "Therefore, in this study, we sought to examine inhibition of MMP-9 with BB-94 on neutrophil and macrophage activation in caerulein-induced pancreatitis." (PMID 32411205, 2020). "All eight nanobiosensors (arginase, cathepsin B, cathepsin E, MMP1, MMP3, MMP9, neutrophil elastase, and uPA) were used to measure enzymatic activity in serum samples from four different disease groups: localized pancreatic cancer, metastatic pancreatic cancer, pancreatitis, and a ‘healthy’ control." (PMID 40292193, 2024). "In this study, we demonstrated that pancreatic MMP-9 was upregulated, and serum MMP-9 was elevated during caerulein-induced pancreatitis." (PMID 32411205, 2020). "MMP9 detected both localized and metastatic pancreatic cancer as well as pancreatitis, but it was not able to significantly distinguish between localized metastatic pancreatic cancer." (PMID 40292193, 2024).
pancreatitis (continued). "Here, we showed that the mRNA level of MMP-9, but not MMP-2, was upregulated in caerulein-induced pancreatitis (data not shown), suggesting that MMP-9 plays a more predominant role during acute pancreatitis." (PMID 32411205, 2020).
vasculitis (15 papers, 2013 to 2026). "Therefore, MMP9-inhibiting monocytes can suppress the invasion of T lymphocytes into the walls of blood vessels, causing decreasing the density of an immune response that leads to vasculitis." (PMID 38694916, 2024). "When inhibiting MMP9 using anti-MMP9 in a vasculitis mouse model, the study showed a decrease in neoangiogenesis and intimal hyperplasia." (PMID 39698202, 2024). "Of note, in granulomatosis with polyangiitis, another vasculitis mainly affecting small vessels, NETs have been observed to induce the expression of MMP-9 in monocytes, obtaining the capability of tissue invasion." (PMID 38734017, 2024). "In a preclinical model, treatment with an antibody blocking MMP-9 activity was sufficient to arrest vasculitis and prevent vessel wall remodeling." (PMID 39086970, 2022). "Ucn1 stimulated IL6 expression in VSMCs and ICAM1 expression in ECs via cyclooxygenase-2, and promoted microvascular permeability during inflammation, MMP9 expression, and the development of vasculitis." (PMID 25462164, 2014). "MMP9 producing mononuclear cells enable T cells to invade the vascular wall and trigger vasculitis." (PMID 34177566, 2021). "However, MMP2 and MMP9 expression were not indicative of vasculitis risk." (PMID 41009699, 2025). "As such, key members such as MMP-3, MMP-9 and tissue inhibitor of metalloproteinase (TIMP)-1 are increased in PR3-ANCA and MPO-ANCA vasculitis." (PMID 33023023, 2020). "Our study aimed to evaluate the expression patterns of MMP2, MMP9, and IL-1β in human endomyocardial biopsies and to correlate them with established histopathological parameters, such as ACR, AMR, inflammation, vasculitis, the Quilty effect, and immune marker expression." (PMID 41009699, 2025). "MMP-2 and MMP-9 have considerably higher levels in plasma samples of RA patients with vasculitis than from those without vasculitis." (PMID 37998356, 2023). "The following potential proteases for the different CKD aetiologies were identified: ADPKD (MMP7), MCD (CTSB, CTSD, CTSE, MEP1A, MMP7, PGA3), MGN (MMP3, MMP7, MMP9, MMP13, MMP14), IgAN (MMP7), FSGS (MMP3, MMP7), vasculitis (PGA3), nephritis (MMP7, MMP9), nephrosclerosis (MMP7), and DKD (MMP9)." (PMID 32427855, 2020). "MIF and matrix metalloproteinase 9 (MMP9), which is known to control the access of monocytes and T cells to the vascular wall, are increased in both diseases, while CD14 is involved in the activation of monocytes and neutrophils in PR3-ANCA vasculitis." (PMID 33023023, 2020). "For this reason, MMP9 resulted the most promising biomarker for the discrimination between FIR 0 and FIR 3 stratified in function of MIR value and of presence or absence of funisitis, vasculitis of umbilical vein or artery and vasculitis of chorioamniotic vessels." (PMID 34848816, 2021).
acute liver failure (14 papers, 2013 to 2025). Rapid deterioration of liver function causing encephalopathy and coagulopathy. "Significant attenuation of acute liver failure symptoms after the combined administration of LPS and D-galactosamine was also observed in MMP-9-deficient mice." (PMID 36289761, 2022). "Experiments have shown that the expression of MMP9 in the damaged liver increases significantly when acute liver failure is induced by LPS, etc.; in addition, MMP9 also plays a certain role in acute hepatitis." (PMID 39534507, 2024). "In acute liver failure induced by LPS and D-galactosamine in hamsters, augmentation of chymase and MMP-9 activities were observed, although they were dose-dependently attenuated by treatment with a chymase inhibitor." (PMID 36289761, 2022). "Previous reports have demonstrated that chymase inhibition significantly reduced MMP-9 levels and attenuated the severity of acute inflammatory diseases, such as indomethacin-induced small intestinal inflammation and acute liver failure." (PMID 34830195, 2021). "TY-51469 has been reported to improve inflammatory diseases, such as indomethacin-induced small intestinal inflammation and acute liver failure, along with the reduction of MMP-9." (PMID 34830195, 2021). "A recent study showed increased MMP9 contributes to brain extravasation and the onset of coma, which can be blocked with an MMP9 monoclonal antibody in an acute liver failure mouse model." (PMID 32878052, 2020). "Geervliet and Bansal found highly significant increase in MMP-9 expression in acute liver failure." (PMID 38467965, 2025). "Collectively, diacerein ameliorated cerebral edema and maintained BBB integrity via modulation of TLR4/AQP4/MMP-9 axis thus may decrease the progression of HE induced in acute liver failure." (PMID 39556255, 2024). "As a consequence of malignant hilar biliary obstruction, acute liver failure might occur with increased MMP-9 expression and contribution to brain extravasation due to the loss of blood–brain barrier integrity." (PMID 36837539, 2023). "One of the studies focused on gaining insights into the function of MMP-9 found MMP-9 to have highly increased expression during acute liver failure and fulminant liver failure, with contribution to brain extravasation and edema due to the loss of blood–brain integrity." (PMID 36837539, 2023). "This indicates that the development of acute liver failure might be a result of MMP-9 activation by chymase, and that chymase inhibition might be a useful strategy for attenuation of acute liver failure symptoms." (PMID 36289761, 2022). "In acute liver failure, MMP9 also degrades occludin and CLDN5 to increase vascular permeability." (PMID 33799999, 2021). "Numerous studies have suggested that MMP-9 played a key role in the modulation of BBB permeability in various conditions such as head injury, acute liver failure, focal or generalized ischemia, and reperfusion in the central nervous system." (PMID 35627746, 2022). "Treatment with MMP-9 chelator GM6001 can reverse disruption of claudin-5 and BBB permeability in brain edema of mice with acute liver failure." (PMID 23505411, 2013).
acute myeloid leukemia (14 papers, 2012 to 2025). Acute myeloid leukemia (AML) is a group of neoplasms arising from precursor cells committed to the myeloid cell-line differentiation. "MMP‐2 and MMP‐9 are assumed to be particularly important for cell transmigration, and the association of cell surface between MMP‐2, MMP‐9 and integrins has been implicated in the progression and growth of chronic myeloid leukaemia and acute myeloid leukaemia cells." (PMID 33566449, 2021). "The obtained results show that the expression of MMP2 and MMP16 genes is reduced while the expression of MMP9 is unchanged in patients with acute myeloid leukemia." (PMID 34035811, 2021). "In the present study, changes in mRNA expression levels of selected metalloproteinase genes (MMP2, MMP9, and MMP16) in acute myeloid leukemia were evaluated." (PMID 34035811, 2021). "Secreted matrix metalloproteinases (MMP)-2 and MMP-9 and membrane-anchored aminopeptidase-N/CD13 are abnormally expressed in human acute myeloid leukaemia (AML)." (PMID 25246708, 2014). "In addition, the activity of MMP‐2 and MMP‐9 may be related to an aggravated course of acute myeloid leukaemia, implying an interplay between MMP‐2/MMP‐9 and T‐ALL." (PMID 33566449, 2021). "The expression level of the MMP2, MMP9, and MMP16 genes does not depend on the presence of cytogenetic changes in cancer cells and gender and age of patients with acute myeloid leukemia." (PMID 34035811, 2021). "The cells of people with acute myeloid leukemia have a lower relative gene expression level of the MMP2 and MMP16 but no MMP9 compared to patients without cancer." (PMID 34035811, 2021).
Airway obstruction (14 papers, 2005 to 2025). Obstruction of conducting airways of the lung. "Furthermore, a low ratio of MMP-9/TIMP-1 (tissue inhibitor of metalloproteinase 1) has been associated with airway obstruction, suggesting that an excess of TIMP-1 compared to MMP-9 could be responsible for airway remodeling." (PMID 22906131, 2012). "In fact, dysregulated MMP9 is a marker of airflow obstruction and diminished lung function in obstructive lung diseases." (PMID 33732255, 2021). "In patients with COPD, MMP‐9 levels were significantly correlated (r = −0.223, P = 0.03) with the degree of airway obstruction." (PMID 28004483, 2017). "To further investigate if the differences in fMLF induced CXCL8 and MMP-9 in controlled and uncontrolled asthmatics were related to airway obstruction, we performed correlation analysis." (PMID 26663987, 2015). "A feature of obstructive lung disease is an increase in MMP-9." (PMID 28352288, 2017). "This may suggest that IL-8, a chemoattractant of neutrophils and an activator of MMP-9, plays a role in the development of airway obstruction." (PMID 15850494, 2005). "Similarly, Beeh and colleagues demonstrated that both MMP-9 and TIMP-1 were elevated in COPD patient sputum, and MMP-9 negatively correlated with airway obstruction but not with either diffusion capacity or vital capacity." (PMID 36935521, 2023).
carotid atherosclerosis (14 papers, 2014 to 2023). A thickening and loss of elasticity of the walls of carotid arteries that occur with formation of atherosclerotic plaques. "Several reports have shown that MMP‐9 polymorphisms are associated with carotid atherosclerosis and increased IS risk." (PMID 31012282, 2019). "Extensive evidence showed MMP‐9 polymorphisms were significantly associated with carotid atherosclerosis and increased IS risk." (PMID 31074588, 2019). "A synthesis of available evidence suggested that MMP9–1562C/T polymorphism was a risk factor for CHD, and MMP9 serum levels were consistently associated with markers of carotid atherosclerosis and lesion vulnerability." (PMID 29403392, 2018). "In carotid atherosclerotic disease, MMP-9 is associated with the development of unstable plaques." (PMID 26377769, 2016). "Furthermore, an additional study identified that increased expression levels of MMP-9 were associated with intraplaque hemorrhage in a swine model of vulnerable carotid atherosclerosis." (PMID 25667675, 2015). "MMP9 can act as a collagenases or a gelatinase and appears to be a biomarker for carotid atherosclerosis and cancerous tumours, along with being elevated in the plasma of Alzheimer’s patients." (PMID 36498929, 2022). "It supports previous results showing enhanced MMP-9 mRNA expression in PBMCs or isolated monocytes from patients with CAD or carotid atherosclerosis." (PMID 25153995, 2014). "The rs3918242 polymorphism in the MMP‐9 promoter may reduce the rate of transcription by inhibiting protein binding, which downregulates MMP‐9 expression, and is associated with carotid atherosclerosis and increased IS risk." (PMID 31012282, 2019). "Furthermore, the MMP-9/TIMP-1 ratio has been proposed as a stronger independent predictor of coronary and carotid atherosclerosis." (PMID 37759829, 2023). "With the increasing degree of carotid atherosclerosis in patients with ICVD, the levels of Cyst‐C and MMP‐9 and homocysteine (Hcy) were significantly increased, and juvenile Cyst‐C, MMP‐9, and Hcy were independent risk factors for the formation of carotid atherosclerostic plaque (CAP)." (PMID 35620813, 2022). "In the present study, patients requiring carotid revascularization appeared with higher levels of CAVI, MMP-3, MMP-7 MMP-9, and TIMP-1 compared to patients with carotid atherosclerosis under conservative treatment or controls without carotid atherosclerosis." (PMID 37759829, 2023). "In conclusion, patients with established carotid atherosclerosis presented with exaggerated CAVI, MMP-3, MMP-7 MMP-9, and TIMP-1 levels compared to individuals without carotid atherosclerotic plaques." (PMID 37759829, 2023).
dengue (14 papers, 2010 to 2025). "In DENV infection, increased levels of MMP-2, MMP-9, and MIF have been associated with increased risk of dengue severity, and both MMP-9 and MIF were reported to induce vascular hyperpermeability." (PMID 34882753, 2021). "Notably, MMP‐2 and MMP‐9 levels are significantly elevated in severe dengue and have been associated with impaired immune responses and increased disease complications in affected patients." (PMID 40910405, 2025). "Because a previous study has indicated that an increase in circulating MMP-9 levels is associated with dengue disease severity, we first examined whether NS1 induces MMP-9 secretion." (PMID 29702687, 2018). "Notably, high circulating levels of MMP-9 have been associated with dengue severity." (PMID 33322218, 2020). "In particular, interleukin‐10, interferon‐gamma and matrix metalloproteinases (MMP‐2 and MMP‐9), all of which are elevated in severe dengue, have been shown to enhance the production of sHLA‐G." (PMID 40910405, 2025). "As metalloproteinases acts as key modulators of extracellular matrix, MMP-9, an enzyme that degrades type IV collagen, was also observed being expressed by hepatocytes, monocytes and macrophages in dengue-liver tissues." (PMID 37457689, 2023). "We also noticed that the concentrations of MMP-9 protein in the serum samples of severe dengue patients increased over the course of DENV infection." (PMID 34310658, 2021). "Further study monitoring the sequential changes in the serum levels of MMP-9 and other glycocalyx-related molecules along with disease development is required to clarify their roles in dengue pathogenesis." (PMID 29702687, 2018). "Interestingly, among several MMPs related to CD147 activation, we measured MMP-9 in the serum of dengue patients." (PMID 35631030, 2022). "MMP-9 plays a key role in other viral induced glycocalyx degradation, such as in dengue fever." (PMID 36260622, 2022). "Another recent study indicated that, in dengue virus infection, MMP-9 can also act directly on endothelial cells, hindering cell adhesion and impairing the occlusion junctions of these cells, causing a situation of hyperpermeability observed in severe cases of dengue." (PMID 36558877, 2022). "Therefore, it is possible that the discrepancy in the MMP-9 level in dengue patients between this and previous studies may be due to differences in the timing of sample collection." (PMID 29702687, 2018). "In a murine dengue model, inhibition of MIF abolished NS-1-induced MMP-9 secretion, and this correlated with reduced syndecan-1 shedding, suggesting that MIF is an important factor that mediates vascular pathology in DENV infection." (PMID 34882753, 2021). "We found that the levels of MIF, HPA-1, MMP-9, and CD138 were all increased in the serum of dengue patients." (PMID 29702687, 2018). "In this study, we first observed that the concentrations of NS1, MIF, HPA-1, MMP-9 and CD138 in the serum of dengue patients were increased." (PMID 29702687, 2018). "Elevated serum levels of an ever increasing list of soluble mediators (such as TNFα, IL-6, C5a, VEGF, MMP-9 and others) have been measured in DHF/DSS patients and represent hallmarks of severe dengue." (PMID 24699622, 2014). "The concentrations of MMP-9 were also significantly elevated in dengue patients with warning signs but not in severe dengue patients." (PMID 29702687, 2018). "In this study, we observed that among NS1, MIF and glycocalyx degradation-related molecules, the HPA-1, metalloproteinase 9 (MMP-9) and syndecan 1 (CD138) serum levels were all increased in dengue patients, and only NS1 and MIF showed a positive correlation with the CD138 level in severe patients." (PMID 29702687, 2018). "This study suggests the role of MMP9 and MMP2 in dengue pathogenesis." (PMID 24727912, 2014).
dengue (continued). "Although secreted factors from supernatants of dengue-infected monocytes or dendritic cells such as MCP-1 and MMP-9 were shown to mediate disruption of permeability functions in HUVECs these studies did not investigate the effect of direct infection of primary endothelial cells on barrier functions." (PMID 23894488, 2013).